RNU6-79P (RNA, U6 small nuclear 79, pseudogene)
Synonyms: RNU6-79
Gene: Small nuclear RNA gene on chromosome 13 (72,881,108 to 72,881,214, reverse strand). Ensembl gene ENSG00000199381.
Homologues: Orthologues: chimpanzee U6 (97% identical), pig U6 (80% identical). Paralogues in human: RNU6-744P (85% identical), RNU6-1060P (82% identical), RNU6-1287P (82% identical), RNU6-188P (82% identical), RNU6-698P (82% identical), RNU6-83P (82% identical), RNU6-1316P (81% identical), RNU6-345P (81% identical), RNU6-371P (81% identical), RNU6-422P (81% identical), RNU6-43P (81% identical), RNU6-455P (81% identical), and 1287 more.